NOX4 (NADPH oxidase 4)
Diseases named in the same sentence as NOX4 in open-access papers (continued):
Sharing a sentence is not in itself a finding about the gene and the disease.
Infertility (1 paper, 2022). "We are currently collecting endometrium samples to unravel the pathways and interactions of the miR-375/NOX4 axis with other critical mechanisms in decidualization to determine their precise relevance to combat infertility." (PMID 35075615, 2022). "However, further investigations are required to ascertain the physiological and clinical relevance of the miR-375/NOX4 axis in infertility." (PMID 35075615, 2022). "Taken together, we inferred that upregulation of miR-375 and downregulation of NOX4 in the endometrium inhibit decidualization leading to infertility and thereby suggest that miR-375/NOX4 axis plays an important role in pregnancy and could be a potential target for combating infertility." (PMID 35075615, 2022). "Moreover, NOX4 expression was downregulated in the secretory phase of endometrium in the samples collected from patients with infertility (although not significantly compared to normal secretory phase)." (PMID 35075615, 2022).
inflammatory bowel disease (1 paper, 2020). A spectrum of small and large bowel inflammatory diseases of unknown etiology. "•NOX4 is elevated in inflammatory bowel disease strictures and inflamed biopsies." (PMID 33059312, 2020).
intracranial aneurysm (1 paper, 2023). "In intracranial aneurysm, a VSMC phenotypic switch is reported that is mediated by increased TRPC6, calcineurin and NFaT expression that leads to enhanced NOX4, p22phox and p47phox expression and ROS production followed by the progression of intracranial aneurysm." (PMID 37759492, 2023).
iron-overload (1 paper, 2022). "NAC can scavenge ROS, inhibit NOX4 expression, and ameliorate iron-overload-induced apoptosis." (PMID 36139457, 2022).
keratoconus (1 paper, 2023). A degenerative, structural disorder of the eye, characterized by a cone-shaped protrusion of the cornea. "Finally, we identified three genes, NOX4, FNDC3B, and ADAMTS17, present in regions of significant local covariance that also have known associations with both keratoconus and body height." (PMID 37561511, 2023).
kidney stone (1 paper, 2019). "OA inhibits NOX4 expression and avoids adhesion of calcium oxalate crystals, possibly to be used for the prevention of kidney stones." (PMID 31117291, 2019). "The NOX4 protein plays a vital role in kidney stone formation." (PMID 31117291, 2019). "In conclusion, OA could be used as a NOX4 inhibitor to prevent kidney stones." (PMID 31117291, 2019).
lentivirus infection (1 paper, 2021). Virus diseases caused by the Lentivirus genus. "A2780 stable cell lines with NOX4 knockdown were obtained through the shNOX4 lentivirus infection and puromycin selection." (PMID 34209278, 2021).
leukocytosis (1 paper, 2022). "Unexpectedly, Nox4 deletion in Flt3ITD/wtMx1-Cre + background induced a further increase in leukocytosis in a gene-dose-dependent manner." (PMID 35348887, 2022).
Listeria-infection (1 paper, 2010). "Thus, ROI production by Nox4 appears to be both necessary and sufficient to induce horizontal cell-cell communication in intestinal epithelial cells leading to chemokine secretion in neighbouring cells in response to Listeria infection." (PMID 21124989, 2010). "Although enhanced Nox4 mRNA expression was shown to result in increased ROI production, the initiation of Nox4-dependent ROI production upon Listeria infection was noted as early as 5–10 minutes after bacterial challenge." (PMID 21124989, 2010). "Importantly, downregulation of Nox4 expression in epithelial cells by siRNA interference significantly reduced Cxcl-2 secretion and ROI production upon Listeria-infection." (PMID 21124989, 2010).
malignant pleural mesothelioma (1 paper, 2023). A malignant neoplasm that arises from mesothelial cells in the pleura and shows a diffuse growth pattern. "In malignant pleural mesothelioma, DPI treatment and knockdown of Nox4 attenuated phosphorylation of AKT and ERK, leading to a decrease in ROS generation and cell viability." (PMID 37189846, 2023).
medulloblastoma (1 paper, 2021). A malignant, invasive embryonal neoplasm arising from the cerebellum. "An additional study demonstrated high level expression of Nox4 in medulloblastoma." (PMID 33799550, 2021).
metastatic cancers (1 paper, 2023). A carcinoma which has spread from the original site of growth to another anatomic site. "In our meta-analysis, we chose 18 publications with a total of 1060 patients who had metastatic cancers to investigate the relationship between NOX4 overexpression and OS." (PMID 38012557, 2023).
muscle atrophy (1 paper, 2022). The loss of muscle tissue due to inactivity or disease. "Muscle atrophy is one of the major side effects of DEX, with the induction of NOX4 and apoptosis after muscle injury and microvascular rarefaction." (PMID 36010575, 2022).
myeloid malignancies (1 paper, 2022). "The role of NOX4 in myeloid malignancies appears highly context-dependent and its inactivation results in either enhancing or inhibitory effects." (PMID 35348887, 2022).
myopia (1 paper, 2025). "iNOS, NOX1, and NOX4 transcripts’ expressions are significantly different between myopia and high myopia, implying a differential oxidative stress signature." (PMID 40650128, 2025). "Herein, we observed an increased expression of transcripts specific to iNOS and two metabolic enzymes, NOX-1 and NOX-4, and these targets were particularly increased in high myopia with respect to myopia." (PMID 40650128, 2025).
myxoma (1 paper, 2024). A benign soft tissue neoplasm characterized by the presence of spindle and stellate cells, lobulated growth pattern, and myxoid stroma formation. "Fibroblasts within myxomas exhibit an activated state, characterized by elevated expression of well-known activated fibroblast markers 18such as POSTN, NOX4, FAP, and COL1A2." (PMID 39090109, 2024).
nephrogenic diabetes insipidus (1 paper, 2014). Nephrogenic diabetes insipidus (NDI) is characterized by polyuria with polydipsia, recurrent bouts of fever, constipation, and acute hypernatremic dehydration after birth that may cause neurological sequelae. "Data of the present study raise the intriguing prospect that NOX4 could represent an attractive target for treatment of disorders associated with deregulation of cAMP signaling in the CCD, such as nephrogenic diabetes insipidus (NDI) and polycystic kidney disease (PKD)." (PMID 24466344, 2014).
neuropathic pain (1 paper, 2018). Chronic pain caused by damage to nerve fibers. "The expression of miR-23b was decreased, while NADPH oxidase 4 (NOX4), the target gene of miR-23b was up-regulated in neuropathic pain." (PMID 29615865, 2018).
ocular toxoplasmosis (1 paper, 2013). Ocular toxoplasmosis is an infection in the eye caused by the parasite, Toxoplasm a gondii. "Down-regulation of Nox4 in T. gondii infected human RPE cell may represent a novel mechanism of blood-retinal barrier breakdown and pathological retinal in ocular toxoplasmosis." (PMID 23824914, 2013).
oral diseases (1 paper, 2014). "In conclusion, we demonstrated that the interplay of NOX4 and redox systems is crucial for ROS formation which plays a pivotal role during oral diseases." (PMID 25374447, 2014).
Pan (1 paper, 2021).
parasite infection (1 paper, 2013). "According to Nox4 siRNA experiments, it is also indicated that Nox4 is the important component for innate immune defense mechanism of host cell against parasite infection and it is the major target for T. gondii to suppress hostile intracellular ROS level." (PMID 23824914, 2013).
Peri-Implantitis (1 paper, 2019). An inflammatory process with loss of supporting bone in the tissues surrounding functioning DENTAL IMPLANTS. "ROS production such as NADPH oxidase and NOX4 was up regulated in peri-implantitis and down regulated in control samples." (PMID 31878038, 2019).
Pleural effusion (1 paper, 2019). The presence of an excessive amount of fluid in the pleural cavity. "In human data, adults with tuberculous pleurisy had higher NOX4 levels in pleural effusion compared to adults with transudate." (PMID 30669315, 2019). "While the expression of NOX4 protein was remarkable in pleural effusions of adults with tuberculous pleurisy, it was undetected in pleural effusions with adults with transudate." (PMID 30669315, 2019). "The NOX4 protein expression was measured in pleural effusion in human adults by Western blotting and immunoprecipitation." (PMID 30669315, 2019).
postmenopausal osteoporosis (1 paper, 2020). Metabolic disorder associated with fractures of the femoral neck, vertebrae, and distal forearm. "Collectively, our results suggest that GTE precludes excessive bone loss due to postmenopausal osteoporosis by inducing bone formation through Bmp2-Smads 1/5/8-Runx2 signaling and interrupts osteoclastogenesis via RANKL/OPG binding and lowered Nox-4 activity." (PMID 33096661, 2020).
proliferative diabetic retinopathy (1 paper, 2015). Advanced retinopathy due to diabetes mellitus characterized by the formation of new vessels in the retina. "In the current study, we investigated the role and mechanism of Nox4 in regulation of retinal neovascularization (NV), a hallmark of proliferative diabetic retinopathy (PDR), using a mouse model of oxygen-induced retinopathy (OIR)." (PMID 25866826, 2015).
prostate (1 paper, 2023). "Elevated NOX4 expression was observed in prostate patients with reduced survival." (PMID 37664042, 2023).
psoriatic arthritis (1 paper, 2024). Joint inflammation associated with psoriasis. "The identification of NOX4 variants in PAM provides novel insights into the genetic basis of this severe form of psoriatic arthritis." (PMID 38379095, 2024). "Our study identified NOX4 as the first candidate susceptibility gene for psoriatic arthritis mutilans (PAM), the rarest and most severe form of psoriatic arthritis." (PMID 38379095, 2024).
renal angiomyolipomas (1 paper, 2018). "Consistent with our in vitro data, we confirmed our observation of increased Nox4 protein expression and augmented ROS levels in the kidneys of Tsc2+/− mice and renal angiomyolipomas obtained from patients with TSC." (PMID 29491408, 2018). "In the present study, using renal proximal tubular cells, tuberin heterozygous mouse and patient-derived renal angiomyolipomas, we have identified the NADPH oxidase isoform Nox4 as the source of ROS due to tuberin deficiency." (PMID 29491408, 2018). "Similarly, we found elevated levels of Nox4 in the renal cortex of Tsc2+/− mice and in the renal angiomyolipomas from TSC patients." (PMID 29491408, 2018). "Similarly, renal angiomyolipomas from patients with TSC exhibited significantly higher levels of Nox4, as compared to the normal kidneys." (PMID 29491408, 2018).
renal hypertension (1 paper, 2021). Hypertension caused by the kidney's hormonal response to narrowing or occlusion of the renal arteries. "Nox4 has been linked to renal hypertension and sodium retention in Dahl salt-sensitive rats, where volume expansion is considered to be the main cause of salt-sensitive hypertension." (PMID 34356336, 2021).
rhabdomyolysis (1 paper, 2025). Necrosis or disintegration of skeletal muscle often followed by myoglobinuria. "However, whether NOX4 blockade can reduce the risk of AKI in patients with rhabdomyolysis remains unknown." (PMID 41154471, 2025).
Right ventricular hypertrophy (1 paper, 2019). In this case the right ventricle is more muscular than normal, causing a characteristic boot-shaped (coeur-en-sabot) appearance as seen on anterior- posterior chest x-rays. "In the MCT-exposed rat, pharmacologic Nox4 inhibition is effective at preventing increases in right ventricular hypertrophy and systolic pressure, and measures of pulmonary arterial stiffness." (PMID 30841544, 2019). "In one, neither global constitutive nor global inducible Nox4 deficiency had any effect on right ventricular hypertrophy and systolic pressure, or pulmonary vascular remodeling." (PMID 30841544, 2019).
serous ovarian carcinomas (1 paper, 2017). "By subtype, serous ovarian carcinomas demonstrated NOX4 overexpression in 8/8 tissues (100%) and mucinous ovarian tissue displayed moderate to strong NOX4 staining for 7/9 (78%), samples, relative to the corresponding normal ovarian tissues 3/8." (PMID 28578276, 2017).
sleep disorder (1 paper, 2025). A change from the patient's baseline sleeping pattern, in the hours slept and/or an alteration/dysfunction in the stages of sleep. "Finally, the circItm2b/Sirt1/Nox4 signaling axis was validated for its involvement in sleep disorders following TBI." (PMID 39962534, 2025). "Then, the expression of Nox4, Clock, and Bmal1 were detected to identify how circItm2b exerted its function in TBI and in subsequent sleep disorders after TBI." (PMID 39962534, 2025).
thrombosis (1 paper, 2020). "The present study showed that ALR-S significantly downregulated plasma levels of H2O2, LDH, and MDA and the expression of endothelial NOX4 and upregulated SOD activities in FeCl3-induced artery thrombosis in rats." (PMID 32308808, 2020).
thyroid follicular carcinoma (1 paper, 2019). "Data obtained from human thyroid follicular carcinoma cells implicated NOX4 as one of the mediators of this TGF-β resistance as siRNA-mediated silencing of NOX4 countered TGF-β inhibitory effect on cell proliferation." (PMID 31083324, 2019).
transitional cell carcinomas of (1 paper, 2017). "NOX4 positive expression was detected in 19/19 transitional cell carcinomas of the bladder; more than 50% of the samples were high positive, compared to the corresponding normal bladder epithelial tissue where the majority were low positive (87%)." (PMID 28578276, 2017).
triple-negative breast carcinoma (1 paper, 2025). An invasive breast carcinoma which is negative for expression of estrogen receptor (ER), progesterone receptor (PR), and human epidermal growth factor receptor 2 (HER2). "Similarly, furanodienone induces apoptosis in CRC cells through ROS production originating from NADPH oxidase 4, and glycyrrhetinic acid activates NADPH oxidases to promote ROS accumulation and ferroptosis in triple-negative breast cancer cells." (PMID 40722996, 2025).
tuberculous pleurisy (1 paper, 2019). "However, exploring the possible mechanism of NOX4 in autophagy inhibition in tuberculous pleurisy is still needed to identify the potential therapeutic target." (PMID 30669315, 2019). "However, the role of NOX4 in tuberculous pleurisy has never been investigated." (PMID 30669315, 2019).
ulcerative colitis (1 paper, 2020). An inflammatory bowel disease involving the mucosal surface of the large intestine and rectum. "NOX4 was upregulated in inflamed mucosal tissue of CD and ulcerative colitis (UC) patients, in CD ileal strictures, and in mice with intestinal inflammation." (PMID 33059312, 2020).
Zinc deficiency (1 paper, 2023). A deficiency of the essential metal Zinc; an essential cofactor for many enzymes. "In this context, the downregulation of Nox4 observed in zinc deficiency could promote depression of the insulin cascade." (PMID 38260166, 2023). "Of note, by contrast, Nox4 is downregulated in zinc deficiency." (PMID 38260166, 2023).
tumor (234 papers, 2010 to 2026). "Recent studies have indicated that NOX4 is overexpressed in GC and positively associated with tumor size and prognosis." (PMID 39991587, 2025). "Research has shown that in the tumor microenvironment of PCa, the Nox4 subtype of NADPH oxidase is highly expressed in the stromal fibroblasts surrounding the tumor and is closely associated with the abnormal activation of transforming growth factor-β (TGF-β)." (PMID 40918147, 2025). "In vitro assays (cell proliferation, colony formation, wound healing, and Seahorse metabolic analyses) and in vivo orthotopic tumor studies assessed the impact of NOX4 loss." (PMID 39991149, 2025). "The deletion of the NOX4 gene is associated with higher tumor grades and worse recurrence-free and overall survival rates." (PMID 39544286, 2024). "Overexpression of NOX4 in non-tumor breast cells has been associated with increased senescence, cellular transformation, and resistance to apoptosis, suggesting an oncogenic role of this enzyme." (PMID 38542437, 2024). "The multifaceted engagement of NOX4 in cancer has generated interest in its potential as a diagnostic and prognostic biomarker, as well as its influence on the tumor microenvironment through interactions with the immune system." (PMID 38663913, 2024). "Studies in vivo demonstrate that blocking Nox4 in 4T1 tumor-bearing mice significantly diminishes lymphangiogenesis and metastatic spread associated with the tumor." (PMID 39090094, 2024). "The correlation between NOX4 overexpression and the BRAFV600E mutation in PTC further underscores the significance of NOX4 in tumor development and aggressiveness." (PMID 39513876, 2024). "NOX4 is essential for maintaining the phenotype of immunosuppressive tumor-associated fibroblasts (CAF)." (PMID 36874093, 2023). "Genetic NOX4 deficiency hampered these processes, resulting in slower growth of fibrosarcomas in a chemically induced tumor model in mice in vivo." (PMID 35269843, 2022). "High tumor lactate is associated with increased risk of metastases and poor patient survival in head-and-neck cancers providing a possible link to NOX4 in these tumors." (PMID 35269843, 2022). "We demonstrate that anti-sense-mediated inhibition of Nox4 significantly reduced the tumor growth generated by tuberin-deficient cells in mice." (PMID 29491408, 2018). "Together these data are strongly suggestive of a pathophysiological relationship between elevated tumor cell‐derived TGFβ and elevated Nox4 expression in the tumor‐associated stroma of clinical PCa." (PMID 29441570, 2018). "Co-injection of HFFF2s transduced with shRNA targeting NOX4 and 5PT cells caused a statistically significant reduction in myofibroblast accumulation (53.2%, 95% CI = 24.1% to 82.2%, P = .01) and tumor growth (37.6%, 95% CI = 6.0% to 69.2%, P = .02)." (PMID 28922779, 2018). "Depletion of NOX1 and NOX4 partially rescued the growth inhibition of PARP1-deficient tumor xenografts." (PMID 29684820, 2018). "Inhibition of Nox4 by anti-sense oligonucleotide blocked the tumor formation in a mouse xenograft model of tuberin-deficient cells." (PMID 29491408, 2018). "We demonstrate for the first time that the tumor‐associated PCa stroma is the predominant source of elevated Nox4 in clinical PCa." (PMID 29441570, 2018). "The work of Boudreau and colleagues reports that over-expression of NOX4 and the associated increase in ROS induce migration of tumor epithelial cells via activation of focal adhesion kinase signaling." (PMID 30065198, 2018). "Other clinical parameters, such as age, gender, tumor size, tumor location and histological differentiation, were barely associated with high NOX4 protein expression." (PMID 28422720, 2017).